CSTF1 (cleavage stimulation factor subunit 1)
Description:
One of the multiple factors required for polyadenylation and 3'-end cleavage of mammalian pre-mRNAs. May be responsible for the interaction of CSTF with other factors to form a stable complex on the pre-mRNA.
Synonyms: CstF-50; CstFp50
Tractability: PROTAC: ubiquitination databases record sites on it; its protein half-life has been measured.
Gene: Protein-coding gene on chromosome 20 (56,392,371 to 56,406,362, forward strand). Ensembl gene ENSG00000101138.
Subcellular location: Nucleus
Subcellular location (Human Protein Atlas): Nucleoplasm
Pathways (Reactome):
Metabolism of RNA: Processing of Intronless Pre-mRNAs; mRNA 3'-end processing; mRNA Polyadenylation
Disease: Dengue Virus-Host Interactions
Gene expression (Transcription): RNA Polymerase II Transcription Termination
Gene Ontology:
Molecular function: protein binding; RNA binding
Biological process: regulation of mRNA 3'-end processing; mRNA 3'-end processing
Cellular component: mRNA cleavage stimulating factor complex; nucleoplasm; nucleus
Genetic constraint (gnomAD): Loss-of-function variants: 1 observed, 40.85 expected, observed/expected ratio (o/e) 0.0245, 90% interval 0.008 to 0.12. The upper end of that interval is the gene's LOEUF score, 0.12, which puts it in group 1 of 6, group 1 being the genes least tolerant of losing a copy. Missense variants: 277 observed, 581.77 expected, observed/expected ratio (o/e) 0.48, 90% interval 0.43 to 0.53. Synonymous variants: 216 observed, 216.23 expected, observed/expected ratio (o/e) 1, 90% interval 0.89 to 1.12.
Homologues: Orthologues: chimpanzee CSTF1 (100% identical), macaque CSTF1 (100% identical), dog CSTF1 (99% identical), guinea pig CSTF1 (99% identical), pig CSTF1 (99% identical), mouse Cstf1 (99% identical), rat Cstf1 (99% identical), tropical clawed frog cstf1 (95% identical), zebrafish cstf1 (90% identical), Drosophila melanogaster CstF50 (54% identical), Caenorhabditis elegans cpf-1 (52% identical). Paralogues in human: WDR55 (19% identical), IK (12% identical).
Diseases named in the same sentence as CSTF1 in open-access papers:
CSTF1 is named in the same sentence as 8 diseases in open-access papers, as found by Europe PMC text mining. Sharing a sentence is not in itself a finding about the gene and the disease. The quoted sentences say what the papers report.
breast carcinoma (3 papers, 2015 to 2025). "It has also been reported that overexpression of AURKA and CSTF1 are associated with detrimental prognosis of breast cancer patients." (PMID 40725120, 2025). "CSTF1, pivotal in DNA damage repair, is linked to increased breast cancer risk in BRCA2 mutation carriers due to CSTF1 mutations." (PMID 39185313, 2024). "The study of gene loci functionally related to HMMR suggests an association between variation in AURKA/CSTF1 and risk of breast cancer among BRCA2 mutation carriers." (PMID 25830658, 2015). "An interaction between rs299290 and rs6064391 (in intron 2 of CSTF1) could reduce breast cancer risk in both BRCA1 and BRCA2 mutation carriers (interaction HRs = 0.87 and 0.73, respectively)." (PMID 25830658, 2015). "Variation in CSTF1, located next to AURKA, was also found to be associated with breast cancer risk in BRCA2 mutation carriers: rs2426618 per-allele HR = 1.10, 95% CI 1.03 – 1.16, p = 0.005 (FDR-adjusted p = 0.045)." (PMID 25830658, 2015).
breast tumors (1 paper, 2015). "Analogous to the HMMR setting, rs2426618 is relatively close (∼30 kb) to the promoter region of AURKA/CSTF1, which is active in mammary epithelial cells and differentially ERα-regulated in poor-prognosis breast tumors." (PMID 25830658, 2015).
gastrointestinal stromal tumor (1 paper, 2024). "In the study on gastrointestinal stromal tumors (GISTs), CSTF1 was involved in a fusion with Aurora kinase A (AURKA)." (PMID 39185313, 2024).
cancer (3 papers, 2013 to 2023). A tumor composed of atypical neoplastic, often pleomorphic cells that invade other tissues. "Similarly, some progressors (CHMP4B, CSTF1, and LSM14B) and suppressors RBPs (ATP5F1A, GTF2E2, RTF1, ELAC2, LRRC47, and MRM3) have never been associated with COAD or READ, but present oncogenic properties in other cancer types." (PMID 37384253, 2023). "Worthy of note, we also identified RBPs that are unique for each cancer type and others (e.g., CSTF1) that have been never related to cancer." (PMID 37384253, 2023).
CSTF1 also shares sentences with these, for which no sentence is quoted: tumor (3 papers); prostate carcinoma (2); mastitis (1); viral infection (1).